TOP2A (DNA topoisomerase II alpha)
Diseases named in the same sentence as TOP2A in open-access papers (continued):
Sharing a sentence is not in itself a finding about the gene and the disease.
cancer (continued). "DLX4, a homeobox gene, overexpressed in several cancers, was shown to reduce sensitivity of tumor cells to TOP2A poisons by stimulating repair of DSB by non-homologous end joining." (PMID 26560244, 2015). "Furthermore, many genes in cancer-related pathways were also over-expressed in high CIN samples including proliferation (ASPM, CKS1B, MCM gene family, TOP2A, TTK, TYMS) and cancer testis antigens (MAGE family)." (PMID 23840451, 2013). "Here we showed that bDMC irreversibly induces DSBs in cancer cells, but not in normal cells, by targeting TOP2A activity and expression." (PMID 23928695, 2013). "The subgroup of patients with ER/PR-negative cancers without amplification of TOP2A in particular had the worst RFS rates (HR = 0.29, 95% CI 0.13 to 0.65, P = 0.001) and the worst OS rates (HR = 0.28, 95% CI 0.10 to 0.76, P = 0.008)." (PMID 21288332, 2011). "Only a few studies found that there was no benefit to treating patients with HER2-positive cancer with anthracyclines or that TOP2A amplification had no predictive value." (PMID 21288332, 2011). "Similarly, MVP and genes encoding for Type I and Type II topoisomerases, such as TOP1, TOP2A, and TOP2B—known to contribute to cancer chemoresistance—showed the same negative association pattern." (PMID 40806276, 2025). "This indicates that, the TOP2A may not regulate the cancer stem cell self-renewal function directly by regulating through Oct-4 and Sox2 rather it regulates by other mechanism." (PMID 38957610, 2024). "Here, several growth-associated genes were up-regulated, including RNA helicase (HELLS), PRR11, CDCA8, and DNA topoisomerase 2 (TOP2A), HMGB2, EIF2B4, and CDKN3, which are thought to serve important functions during growth stimulation, many of which are known to be up-regulated in various cancers." (PMID 37907238, 2024). "Thus, TOP2A plays an important role in regulating genomic stability, and its dysfunction leads to chromosomal rearrangements and cancer, and therefore, it is not surprising that TOP2A is a target for various anticancer drugs." (PMID 37048139, 2023). "DNA topoisomerase II alpha activates cell cycle progression from the G2 to the M phase by inhibiting CHK1 phosphorylation (CHK1, checkpoint kinase 1, is the protein product of the CHEK1 gene), promoting the epithelial-to-mesenchymal transition and cancer cell invasion." (PMID 38136356, 2023). "While TOP2A had no prognostic values in other types of cancers (HR ≤ 1, P-value > 0.05)." (PMID 37980167, 2023). "Therefore, it is likely that that Frondoside A inhibits the proliferation and metastasis of cancer cells by down-regulating CDK1, CDC20, TOP2A and up-regulating CNN1.It should be noted that the free binding energy between Frondoside A and CDK1 was the lowest, measuring -10.7 kcal/mol." (PMID 38144520, 2023). "Moreover, the expression of TOP2A mRNA between normal and tumor tissues for those cancers without data of normal control in the TCGA database was performed using the data of corresponding normal tissues from the GTEx dataset as normal controls." (PMID 35873470, 2022). "Topoisomerase II a (TOP2A) can be a useful gene in determining whether TNBC patients would have a good response to anthracycline therapy, which is the mainstay treatment in TNBC cancer." (PMID 36407327, 2022). "However, no pan-cancer analysis about the function and the upstream molecular mechanism of TOP2A is available." (PMID 35778520, 2022). "The six hub genes (BIRC5, TOP2A, FANCI, NCAPG2, RAD51, and RRM2) were reported to be critical to regulate cell cycle, and their abnormal expression could lead to development and progression of cancers." (PMID 32902196, 2020). "Finally, we asked the question whether the two MRs (TOP2A and CENPF) are especially significant for CC compared to other cancer types." (PMID 33023625, 2020).
cancer (continued). "Likewise, we observed significant positive correlations of TOP2A and RACGAP1 expression levels with DEPTH scores in 13 and 15 cancer types, respectively (FDRsp < 0.05), as well as in pan-cancer (TOP2A: p = 6.98 × 10−93, ρ = 0.21; RACGAP1: p = 4.14 × 10−157, ρ = 0.28)." (PMID 32917965, 2020). "Currently, no data exist about the mitochondrial protein levels of Top2α, Top2β, and Top3β in cancer cells compared to other cell types, but as these topoisomerases participate in mtDNA replication and expression, they should influence the metabolism of cancer cells." (PMID 31027213, 2019). "Furthermore, inhibitors of TOP2A, TTK, and CHEK1, which are already used for treating certain cancers, could potentially be used in ACC treatment." (PMID 30886771, 2019). "The presence of NaClO4 shifts Top2α to a lighter fraction, in a position corresponding to free enzyme (lanes 3 vs 5), thus confirming the ability of NaClO4 to disrupt enzyme-DNA complex in the absence of an anti-cancer drug." (PMID 24809695, 2014). "Moreover, we confirm the clinical importance of identifying the subgroup of patients with ER/PR-negative, TOP2A nonamplified cancer, as they have the worst prognosis." (PMID 21288332, 2011). "Thus, we found that Amplicon Class with TOP2A deletion in ERBB2-amplified BC was associated with shorter time to tumor recurrence and significantly higher risk of cancer recurrence independent of other covariates." (PMID 18702822, 2008). "Moreover, genes that are upregulated and downregulated at both RNA and protein levels across multiple types of cancers were identified and defined as PCUGs and PCDGs, respectively, which encompass a large number of oncogenes such as MKI67, TRIP13, SMC4, UBE2C, CDK1, and TOP2A." (PMID 39884577, 2025). "Furthermore, certain cell cycle–related proteins, including TOP2A, PCNA, MCM2, MCM4, MCM5, MCM6, and MCM7, have also been reported to facilitate cancer cell proliferation, and the enhanced expression of these cell cycle–related proteins may contribute to uncontrolled ESCC cell proliferation." (PMID 38652547, 2024). "In addition, we find that the drug target of idarubicin (TOP2A) and Cytarabine (POLB) form a significant protein-protein interaction network (P < 1.0 × 10−16), indicating that the predictive biomarkers work as the direct interactive proteins of cancer drug targets." (PMID 33362849, 2020). "As TOP2A gene is located adjacent to the ERBB2 gene, it is frequently either co-amplified with or independent of ERBB2 in many cancer types, including UCB43." (PMID 33298978, 2020). "Gene expression analysis showed that clonogenic side population cells in cancers express genes involved in the cell cycle and mitosis (e.g., SKA1, CCNB1, CDC25C, CDC2, BIRC5, CENPE, AURKB, KIFs, TOP2A, ASPM) more strongly than non-side population cells." (PMID 23962337, 2013). "However, unlike cancer, the function of proteins involved in DNA damage response, such as BRCA2 and TOP2A, does not show uncoordinated functions." (PMID 26975659, 2016). "Although Top2a knockout mice have not been described, Topbp1 knockouts die at the same early stage of embryogenesis as Brg1 null homozygotes, and TOPBP1 is involved in normal DNA replication as well as cancer prevention." (PMID 25544751, 2015). "Similarly, two Polish series indicated amplification of TOP2A occurs in a substantial proportion of HER2 non-amplified cancer, however again the definition of amplification (TOP2A/CEP17>1.25) undoubtedly led to the counting of TOP2A non-amplified tumors as amplified." (PMID 34625570, 2021).
tumor (429 papers, 1996 to 2026). "The expression of Macrophages M0 and tumor mutation burden was correlated with the expression of TOP2A (P < 0.05)." (PMID 41284119, 2025). "Loss of ARID1A compromises genomic stability, resulting in TOP2A-mediated dsDNA breaks that can accumulate and contribute to tumor progression and genomic instability." (PMID 40750787, 2025). "It has been demonstrated that TOP2A is associated with tumour proliferation, metastasis and resistance to chemotherapy." (PMID 40271060, 2025). "TNBCvax, which targets three key tumor-associated antigens (TOP2A, HIF-1α, and IGF-1R), offers superior tumor prevention and immunogenicity compared to single-antigen vaccines." (PMID 40969744, 2025). "The findings demonstrate that CCNA2, CHK1, E2F1, and TOP2A exhibit significant associations with tumor stage and size, whereas CHK2 shows a correlation solely with age." (PMID 40573296, 2025). "TOP2A is overexpressed in various malignancies and is associated with chemotherapy resistance, abnormal cell proliferation, aneuploidy, tumor recurrence, and reduced overall survival." (PMID 40487391, 2025). "In the absence of TOP2A-specific anthracyclines, TOP2B-selective catalytic inhibitors pose a unique opportunity to strategically prevent TOP2B poisoning in the heart while leaving TOP2A in tumours susceptible to anthracycline poisoning." (PMID 40425539, 2025). "We developed TNBCvax, a multi-antigen, multi-peptide vaccine designed to simultaneously target three key tumor-associated antigens: TOP2A, HIF-1α, and IGF-1R." (PMID 40969744, 2025). "Current studies are focused on elucidating the mechanisms underlying TOP2A’s involvement in tumor progression and the development of resistance to treatment." (PMID 40290723, 2025). "In this study, we demonstrated that TOP2A is overexpressed in tumor tissues and associated with prognosis, including in HCC." (PMID 40271060, 2025). "To address this, we developed TNBCvax, a multi-antigen, multi-peptide vaccine targeting three tumor-associated antigens overexpressed in TNBC: TOP2A, HIF-1α and IGF-1R." (PMID 40969744, 2025). "We demonstrated that resistance to CX-5461 was directly correlated with the level of Top2α protein and Top2 activity, not only in a mutated clones derived from a resistant tumor, but also in cell lines in which Top2α levels were downregulated." (PMID 39062087, 2024). "The gene TOP2A, after which this subgroup is named, has been significantly associated with tumor occurrence, invasiveness, therapeutic response, and prognosis." (PMID 39136009, 2024). "Topoisomerase IIα (TOP2A) is an enzyme encoded by the TOP2A gene, which is highly expressed in rapidly dividing cells and can promote tumor proliferation and induce metastasis." (PMID 38593113, 2024). "Further analysis highlighted four specific hub genes—CCNA2, CCNB2, CDK1, and TOP2A—that showed significantly higher expression in HBV‐associated HCC tumor samples compared to normal samples in the GEPIA database." (PMID 38895552, 2024). "We demonstrated that resistance to CX-5461 was directly correlated with the level of Top2α protein and Top2 activity not only in mutated clones derived from a resistant tumor, but also in cell lines in which Top2α level was downregulated." (PMID 39062087, 2024). "Overexpression of TOP2A has been linked to a more aggressive tumor phenotype and is associated with poor prognosis." (PMID 38730293, 2024). "The analyses revealed that high TOP2A expression was associated with the presence of tumor cell spindling (Fisher’s exact test, p = 0.013), mitotic figures (p = 0.042), and capsular invasion (p = 0.001)." (PMID 36656469, 2023). "We also detected a similar upregulation of Top2a, a proliferation marker associated with tumor grade and Ki67 index." (PMID 37727504, 2023). "Aberrant expression of TOP2A is associated with tumor progression, chemotherapy response, and prognosis." (PMID 38008711, 2023).
tumor (continued). "Gene enrichment analysis, DNA methylation, gene mutation, prognosis, and tumor immunity associated with TOP2A in LIHC were investigated." (PMID 37980167, 2023). "In contrast, high levels of HER2, Ki67, and TOP2A were linked to high tumor grade (p < 0.0001 each), but they were unrelated to overall survival." (PMID 38137396, 2023). "The expression level of the TOP2A gene can reflect tumor proliferation and was reported to be associated with peritoneal and hematogenous recurrence." (PMID 35938042, 2022). "TOP2A overexpression associates with the outcomes of patients in multiple tumor types, suggesting its potential carcinogenic effect and prognostic value." (PMID 35778520, 2022). "We validated the loss of TOP2A+ tumor cells, which we also observed by conventional differential expression analysis, using in situ hybridization analysis of etoposide-treated slice cultures from a separate cohort." (PMID 33975634, 2021). "Seventy-two HCC tumor samples were harvested for assessing the association of TOP2A expression with EMT in HCC cells through evaluation of TOP2A, E-cadherin, Snail, and vimentin levels." (PMID 34939898, 2021). "Elevated expression of TOP2A is associated with advanced stage of disease, aggressive phenotype of tumor, and poor prognosis." (PMID 34021129, 2021). "Vice versa, decreased level of TOP2A mutation can induce the loss of the anti-tumor drug targeting and multiple drug resistance development." (PMID 34440090, 2021). "As referenced above, Desmedt and colleagues analyzed tumor tissue from a neoadjuvant clinical trial of anthracycline-based therapy and showed that pCR was associated with TOP2A amplification." (PMID 34625570, 2021). "Molecular mechanisms associated with TOP2A overexpression and tumor progression or chemoresistance still need to be established." (PMID 34638362, 2021). "PD‐L1 expression was associated with TOP2A positivity in 10 of 40 tumor types; hence, doxorubicin/etoposide/epirubicin and immunotherapy is likely to be of benefit." (PMID 31479512, 2020). "An elevated TOP2A expression is observed in many tumor tissues, and significantly associated with MKI67 expression as well as tumor aggressiveness and poor outcome." (PMID 33061942, 2020). "MSI‐H was associated with TOP2A positivity in 4 of 40 tumor types; hence, doxorubicin/etoposide/epirubicin and immunotherapy is likely to be of benefit." (PMID 31479512, 2020). "Mo and Beck characterized TOP2α mRNA splice variants in TOP2α poison sensitive T-lineage tumor cell lines (e.g., CEM, Jurkat, and H9)." (PMID 32566920, 2020). "TOP2A, DNA topoisomerase II alpha encoding a DNA topoisomerase, regulates the topologic states of DNA and controls tumor cell response." (PMID 32685486, 2020). "MYBL2 is known to promote cell proliferation and EMT in many tumor types, and TOP2A is associated with worse prognosis in non‐small‐cell lung cancer patients." (PMID 30913346, 2019). "Abnormal activities of TOP2A and related molecules attribute to the instability of tumor genomes that is linked to tumor progression." (PMID 31083655, 2019). "Higher TOP2A expression was associated with worse NSCLC OS suggesting its probable tumor promoter function and potential survival predictor." (PMID 31528121, 2019). "On the other hand, TOPO1 and TOP2A were significantly underexpressed in RAS-mutated tumours (BH adjusted Mann-Whitney p = 0.023 for both comparisons)." (PMID 31537838, 2019). "Patients with TOP2A amplified tumor had higher risk reductions for relapse and survival compared with normal TOP2A tumor by anthracycline-containing chemotherapy." (PMID 29928479, 2018). "In consistent with previous studies, we found TOP2A protein was significantly associated with high tumor grade and Ki67 index, suggesting that tumors with high level of TOP2A expression were more aggressive." (PMID 29587760, 2018). "In a subgroup analysis of spinal ependymomas, high tumor grade was associated with increased TS and TOP2A expression." (PMID 29487694, 2018).
tumor (continued). "Topoisomerase II alpha (TOP2A) protein has been shown to be a proliferation marker associated with tumor grade and Ki67 index." (PMID 29587760, 2018). "Spearman correlation analysis validated further a significant positive association between levels of Top2a and Ezh2 mRNA levels in 2 independent human primary tumor datasets." (PMID 25605014, 2015). "Further investigation to fully understand factors and mechanisms underlying tumor response to TOP2A inhibiting drugs is needed." (PMID 26560244, 2015). "TOP2A overexpression was detected in 72.5% (29/40) of tumor tissues and significantly associated with HCC tissues (P < 0.001); in other words, it was only found in HCC tumor tissues." (PMID 25695068, 2015). "In line with the role of TOP2A in cell proliferation, we observed strong associations of the proliferation marker Ki67 and tumor grade (which is characterized by Ki67 labelling) with TopoIIa protein and TOP2A mRNA levels." (PMID 22240029, 2012). "TOP2A alterations clearly have a potential role in tumor progression and treatment response, and have been linked to better disease-free survival for patients with HER2+ disease treated with anthracyclines." (PMID 20459607, 2010). "TOP2A amplification was associated with tumor response in this study, but the patients and the end point were quite different than the present study." (PMID 18702822, 2008). "Drug resistance to anti-tumour agents often coincides with mutations in the gene encoding DNA topoisomerase II alpha." (PMID 8630279, 1996). "In particular, CCNA2, CCNB2, CDK1, and TOP2A were found to be significantly upregulated in HBV‐positive HCC tumor samples and may serve as promising diagnostic biomarkers." (PMID 38895552, 2024). "TOP2A was associated with higher tumor grade and advanced pathological stage." (PMID 38730293, 2024). "TOP2A is traditionally known as a duplex DNA ‘strand-passage’ enzyme that resolves entanglements and relieves torsional stress of DNA by the production of DNA double-stranded breaks and its upregulation is associated with the malignancy of several tumours." (PMID 38448751, 2024). "TOP2A, a member of DNA topoisomerase has been involved in the development and progression of multiple tumors associated with the increased cell proliferation and tumor grade." (PMID 38957610, 2024). "TOP2A was associated with growth in HCC tumor cells resulting in metastasis." (PMID 36900109, 2023). "Additionally, associations of TOP2A mRNA expression to other clinical parameters, including death due to the tumor, were found." (PMID 36656469, 2023). "We analyzed the correlation of EZH2 and TOP2A with patients’ clinicopathological variables using HCC data from TCGA database and found that high EZH2 and TOP2A expression was significantly associated with tumor differentiation grade, tumor invasion, TNM stage, and the status of patients with HCC." (PMID 38008711, 2023). "Additionally, over-expression of TOP2A has been associated with aggressive tumor types, tumor recurrence, and poorer survival, thereby indicating the potential of TOP2A as a prognostic marker." (PMID 36656469, 2023). "TOP2A is a proliferation marker associated with Ki-67 index and tumor grade." (PMID 35875123, 2022). "In terms of PDCD1, the expression was positively associated with TOP2A expression in 12 tumor types, including BRCA, HNSC, HNSC-HPV−, HNSC-HPV+, KIRC, LGG, LIHC, LUAD, LUSC, PRAD, THCA (Rho = 0.191) and THYM, but a negative relationship in UCEC (all p values < 0.05)." (PMID 35778520, 2022). "Tumour expression of TOP2A, RRM1, HER2 and ERCC1 may associated with the sensitivity of NMIBC to pirarubicin or gemcitabine treatment." (PMID 35711974, 2022). "Furthermore, TOP2A level is known to have close relationship with the potency of anti-tumor drugs and high level of TOP2A regulating the main pathway of drug susceptibility." (PMID 34440090, 2021). "TOP2A expression was associated with higher tumor grading and shorter 5-year OS." (PMID 34638362, 2021).